OARD1 (O-acyl-ADP-ribose deacylase 1)
Description:
ADP-ribose glycohydrolase that hydrolyzes ADP-ribose and acts on different substrates, such as proteins ADP-ribosylated on glutamate and O-acetyl-ADP-D-ribose. Specifically acts as a glutamate mono-ADP-ribosylhydrolase by mediating the removal of mono-ADP-ribose attached to glutamate residues on proteins. Does not act on poly-ADP-ribosylated proteins: the poly-ADP-ribose chain of poly-ADP-ribosylated glutamate residues must by hydrolyzed into mono-ADP-ribosylated glutamate by PARG to become a substrate for OARD1. Deacetylates O-acetyl-ADP ribose, a signaling molecule generated by the deacetylation of acetylated lysine residues in histones and other proteins. Catalyzes the deacylation of O-acetyl-ADP-ribose, O-propionyl-ADP-ribose and O-butyryl-ADP-ribose, yielding ADP-ribose plus acetate, propionate and butyrate, respectively.
Synonyms: C6orf130; TARG1; MGC19570; dJ34B21.3
Tractability: Small molecule: a structure with a bound ligand is known. PROTAC: ubiquitination databases record sites on it; its protein half-life has been measured.
Target class: Enzyme; Hydrolase
Gene: Protein-coding gene on chromosome 6 (41,033,627 to 41,097,787, reverse strand). Ensembl gene ENSG00000124596.
Subcellular location: Nucleus, nucleoplasm; Nucleus, nucleolus; Chromosome
Subcellular location (Human Protein Atlas): Nucleoli; Nucleoplasm
Gene Ontology:
Molecular function: ADP-ribosylglutamate hydrolase activity; O-acetyl-ADP-ribose deacetylase activity; protein binding; purine nucleoside binding
Biological process: DNA damage response; peptidyl-glutamate ADP-deribosylation; protein de-ADP-ribosylation; purine nucleoside metabolic process
Cellular component: chromosome; nucleolus; nucleoplasm; site of DNA damage
Genetic constraint (gnomAD): Loss-of-function variants: 7 observed, 6.87 expected, observed/expected ratio (o/e) 1.02, 90% interval 0.57 to 1.76. That is too few expected variants to judge how well the gene tolerates losing a copy. Missense variants: 63 observed, 62.69 expected, observed/expected ratio (o/e) 1, 90% interval 0.82 to 1.24. Synonymous variants: 25 observed, 21.4 expected, observed/expected ratio (o/e) 1.17, 90% interval 0.85 to 1.62.
Homologues: Orthologues: chimpanzee OARD1 (100% identical), macaque OARD1 (100% identical), guinea pig OARD1 (97% identical), dog OARD1 (97% identical), mouse Oard1 (95% identical), pig OARD1 (95% identical), rabbit OARD1 (93% identical), zebrafish oard1 (61% identical), Drosophila melanogaster Targ1 (49% identical), Drosophila melanogaster Targ3 (45% identical), Drosophila melanogaster Targ2 (41% identical), rat Oard1 (39% identical).
Diseases named in the same sentence as OARD1 in open-access papers:
OARD1 is named in the same sentence as 1 disease in open-access papers, as found by Europe PMC text mining. Sharing a sentence is not in itself a finding about the gene and the disease. The quoted sentences say what the papers report.
cancer (1 paper, 2020). A tumor composed of atypical neoplastic, often pleomorphic cells that invade other tissues. "MACROD1, MACROD2, and OARD1 (TARG1) exhibit mutations only in 0.9%, 2.6%, and 1% of cancer patient samples, respectively, from over 1000 samples in the cBioPortal curated dataset." (PMID 32151005, 2020).